BDNF (brain derived neurotrophic factor)
Diseases named in the same sentence as BDNF in open-access papers (continued):
Sharing a sentence is not in itself a finding about the gene and the disease.
lung carcinoma (26 papers, 2010 to 2025). "- Involved in the progression of several cancers, such as breast, colorectal, and lung cancer.- Increased BDNF expression has been associated with tumor growth, invasion, and resistance to chemotherapy." (PMID 38375479, 2024). "More recently, we examined the role of mature brain-derived neurotrophic factor (mBDNF) in lung cancer cells as a molecular player implicated in overlapping mechanisms converging at the interface of cancer and neurodegeneration." (PMID 36142659, 2022). "Compared with normal lung, BDNF levels were upregulated in lung cancer cell culture supernatants, linked to lung tumorigenesis, and associated with poor prognosis in NSCLC patients." (PMID 36361620, 2022). "We have previously confirmed that TrkB was overexpressed in lung cancer, BDNF facilitated A549 cell invasion by inducing phosphorylation of Pyk2-tyr402, which is a newly found signaling associated with invasion of lung cancer cells." (PMID 26926340, 2016). "In in vitro study, significantly decreased cell growth and expression of TrkB and BDNF by siTNFR2 transfection were found in A549 lung cancer cells." (PMID 38592583, 2024). "In our study, the expression levels of BDNF/TrkB were significantly lower levels in TNFR2 KO mice xenografted with A549 lung cancer cells compared to WT mice which showed lower development of cancer and SCZ." (PMID 38592583, 2024). "We also found that the expression of BDNF and TrkB was higher in BDNF injected TNFR2 KO A549 lung cancer cells xenograft tumor tissues." (PMID 38592583, 2024). "We next performed the behavior test in BDNF-injected TNFR2 KO mice xenografted with A549 lung cancer cells." (PMID 38592583, 2024). "There was a significant difference in tumor growth between the BDNF-injected TNFR2 KO mice xenografted with A549 lung cancer cells and the TNFR2 KO mice xenografted with A549 lung cancer cells." (PMID 38592583, 2024). "BDNF was reported to accelerate the progression of many cancers, including lung cancer, promoting invasion of lung squamous cell carcinoma." (PMID 37760996, 2023). "Upregulation of BDNF levels in lung cancer cell culture supernatants was observed compared with normal lung and linked to lung tumorigenesis and poor prognosis in NSCLC patients." (PMID 37760996, 2023). "Fourth, the dysfunction of neurotrophins, including BDNF and its receptors TrkB/P75 play an essential role in both mental diseases and lung cancer." (PMID 36417428, 2022). "Blood corticosterone concentration, and levels of cytokines, lung cancer-related factors, brain-derived neurotrophic factor (BDNF) and apoptosis-related factors in the lung, amygdala and hippocampus were measured." (PMID 36417428, 2022). "Silencing BDNF expression was shown to block cell proliferation, promoting cell apoptosis, and thereby blocking the growth of lung cancer cells." (PMID 36361620, 2022). "To further examine the function of other molecular players implicated in overlapping mechanisms that converge at the interface of neurodegeneration and cancer, we chose to focus on BDNF in lung cancer cells in this study." (PMID 34209215, 2021). "BDNF was shown to be upregulated in lung cancer cells compared to normal lung cells and critical for lung tumorigenesis." (PMID 34209215, 2021). "Compared to normal lung cells, the levels of BDNF were reported to be upregulated in lung cancer cell culture supernatants and critical for lung tumorigenesis." (PMID 34209215, 2021). "BDNF was found to be associated with poor prognosis in NSCLC patients, with levels upregulated in lung cancer cell culture supernatants compared with the normal lung counterparts and critical for lung tumorigenesis." (PMID 34209215, 2021).
lung carcinoma (continued). "Silencing BDNF expression blocked cell proliferation and promoted cell apoptosis, thereby conferring a disadvantage to the growth of lung cancer cells." (PMID 34209215, 2021). "TrkB and BDNF were also demonstrated by IHC in patients belonging to Group 1 in both lung cancer and the corresponding brain metastasis." (PMID 33294440, 2020). "BDNF has been reported to be elevated and involved in the tumorigenesis and progression of various human cancer types, including cancers of the lung, stomach, breast, and cervix, as well as hepatocellular carcinoma and chondrosarcoma." (PMID 33817216, 2020). "BDNF-mediated activation of EGFR has been observed in lung cancer and suggests BDNF/TrkB/EGFR cross-talk is a more general mechanism promoting BM." (PMID 30796353, 2019). "Second, previous reports show that EGFR is overexpressed and abnormally activated in lung cancers, and that exogenous BDNF increases TrkB activation and affects cancer cell signaling." (PMID 29312608, 2017). "According to previously published reports and our data, TrkB is overexpressed and abnormally activated in lung cancer, and exogenous BDNF increases TrkB activation and affects its downstream function." (PMID 27456333, 2016). "Our data indicate that BDNF promotes cell proliferation and invasion, and silencing BDNF probably confers the disadvantage to the growth of lung cancer cells." (PMID 26926340, 2016). "In this study, we report the significant expression of BDNF in NSCLC samples and show that BDNF stimulation increases the synthesis of BDNF itself through activation of STAT3 in lung cancer cells." (PMID 27456333, 2016). "In cell studies, the extensive expression and secretion of BDNF were demonstrated in lung cancer cells compared with HBE cells." (PMID 26926340, 2016). "We also reported that the expression and secretion of BDNF were more extensive in lung cancer cells." (PMID 26926340, 2016). "We also examined 110 FFPE sections of lung SCC and ADC by means of immunohistochemistry to reveal the clinical significance of BDNF for lung cancer." (PMID 26926340, 2016). "In contrast, incubation of TrkB expressing cells with BDNF stimulated lung cancer cell migration in the wound closure assay." (PMID 24959744, 2014). "Hypermethylation of genes such as COX7A1, TNFRSF1B, and BDNF, as well as hypomethylation of genes such as CDC6 and KRT8, may be associated with lung cancer compared to benign nodules." (PMID 39036344, 2024). "However, the addition of BDNF (100 ng/ml) into TNFR2 siRNA transfected A549 lung cancer cells recovered cell growth and the expression of TrkB." (PMID 38592583, 2024). "In contrast, our study revealed that BDNF had higher methylation and lower expression in IA, suggesting that BDNF may have distinct functions in early‐stage versus late‐stage lung cancers." (PMID 39036344, 2024). "In this study, we shed light on a molecular mechanism whereby the levels of sE-cad in human lung cancer cell media are enhanced by nicotine, BDNF, and/or β-AR ligands, as well as the intracellular signaling mechanisms employed by sE-cad to increase lung cancer cell survival." (PMID 37760996, 2023). "Our results from this study provide new insights into a molecular mechanism for the regulation of sE-cad levels in human lung cancer cell media by nicotine, BDNF, and/or β-AR ligands, which can likely offer novel therapeutic opportunities aimed at targeting this regulatory network." (PMID 37760996, 2023). "Our findings shed light on an interplay between nicotine, BDNF, and β-Adrenergic receptor signaling in regulating survival of lung cancer cells and chemoresistance which can likely expand therapeutic opportunities that target this regulatory network in the future." (PMID 36361620, 2022).
lung carcinoma (continued). "In comparing two human lung cancer cells, we previously found lower levels of acetylcholinesterase (AChE) and intact amyloid-β40/42 (Aβ), and higher levels of mature brain-derived neurotrophic factor (mBDNF) in the media of H1299 cells as compared to A549 cell media." (PMID 36142659, 2022). "Our results in this study may provide new insights into a molecular mechanism of regulation of cisplatin-induced apoptosis in human lung cancer cells by nicotine, BDNF, and a β-AR blocker." (PMID 36361620, 2022). "TrkB and/or BDNF had also been found in other solid malignancies, such as pancreatic ductal adenocarcinoma, prostate cancer, and lung cancer." (PMID 36120557, 2022). "Similarly, BDNF was more expressed in metastasis than in the corresponding primitive lung cancer from which they originated (2.2 ± 0.6 vs. 1.3 ± 0.5) (p = 0.004)." (PMID 33294440, 2020). "Finally, the expression of TrkB and BDNF was estimated on sample tissue obtained from metastasis of lung cancer different from brain, in particular, liver (n = 13), bone (n = 2), and skin (n = 5)." (PMID 33294440, 2020). "Previously, BDNF and its related receptor signaling system (BDNF/TrkB) have been shown to play important roles in the regulation of cell proliferation and metastasis across many types of cancer, including colon cancer, lung cancer and cancer of the brain." (PMID 28800782, 2017). "To investigate whether STAT3 can, in turn, serve as a mediator of BDNF expression in lung cancer cells, we analyzed the level of phosphorylated STAT3 under serum-deprived conditions by Western blot." (PMID 27456333, 2016). "The suppression of BDNF may provide a significant target for inhibitory strategies for the development of lung cancer, which requires further investigations." (PMID 26926340, 2016). "Additionally, we found that BDNF expression was under the control of STAT3 and was decreased upon the inhibition of STAT3 activity by Stattic in A549 and H1299 cells, thus establishing STAT3 as a critical regulator of BDNF in lung cancer cells." (PMID 27456333, 2016). "The expression of BDNF mRNA variant IX is probably more helpful to the upregulation of BDNF in SCC, and intervening the production of BDNF could be a possible strategy to lung cancer therapy." (PMID 26926340, 2016). "To study whether BDNF/TrkB signaling regulates the activation of STAT3 in lung cancer cells, we examined the level of phosphorylated STAT3 in cells with or without the Trk inhibitor K252a (100 nM)." (PMID 27456333, 2016). "The primary receptor for BDNF, TrkB is critical in lung cancer development." (PMID 26926340, 2016). "Moreover, the BDNF mRNA variant containing exon IX was important to the higher expression in SCC cells, and BDNF was critical to the proliferation and invasion of lung cancer cells." (PMID 26926340, 2016). "Researches focused on the function of BDNF/TrkB in lung cancer were also performed in recent years." (PMID 26926340, 2016). "Our findings shed light on an interplay between nicotine, BDNF, and β-AR signaling in regulating lung cancer cell survival and chemoresistance, which could likely lead to the development of novel therapeutic strategies that target this regulatory network in the future." (PMID 36361620, 2022). "However, the IOD indicative of BDNF protein level was excessively high in lung cancer cells." (PMID 26926340, 2016). "The expression of BDNF detected by Western blotting was significantly increased in BDNF-injected TNFR2 KO mice xenografted with A549 lung cancer cells, but no significant increase was noted in WT mice xenografted with A549 lung cancer cells." (PMID 38592583, 2024). "In previous results, no SCZ-like behavioral changes were observed in TNFR2 KO mice xenografted with A549 lung cancer cells, but significant SCZ-like behavioral changes were observed when BDNF was co-injected into these mice." (PMID 38592583, 2024).
lung carcinoma (continued). "As the significant tumor growth by BDNF injection, significant increase of SCZ-like behavior was observed in TNFR2 KO mice xenografted with A549 lung cancer cells." (PMID 38592583, 2024). "We examined the BDNF and TrkB expression in BDNF-injected TNFR2 KO mice xenografted with A549 lung cancer cells PFC." (PMID 38592583, 2024). "The level of BDNF in serum was significantly increased in BDNF-injected TNFR2 KO and WT mice xenografted with A549 lung cancer cells compared to TNFR2 KO and WT mice xenografted with A549 lung cancer cells." (PMID 38592583, 2024). "The expression level of BDNF and TrkB was also higher in BDNF-injected TNFR2 KO mice xenografted with A549 lung cancer cells tumor tissue." (PMID 38592583, 2024). "Our results showed that APRIL expression was under the control of EGF and BDNF signaling in NSCLC cells, meaning that these two factors are critical inducers of APRIL in lung cancer cells." (PMID 29312608, 2017). "BDNF expression was also evaluated in human bronchial epithelial cells (HBE) and 4 lung cancer cell lines using western blot." (PMID 26926340, 2016). "Our data suggested a novel signaling by which BDNF facilitates the invasion of A549 cells via TrkB/Pyk2/ERK pathway, which possibly contributes to the metastasis of those lung cancer cells." (PMID 20156366, 2010). "The expression of BDNF and TrkB detected by IHC in PFC of TNFR2 KO and TNFR2 KO mice xenografted with A549 lung cancer cells was not significant, whereas in WT and WT mice xenografted with A549 lung cancer cells a significant difference was noted." (PMID 38592583, 2024). "The level of BDNF in serum was significantly increased in WT A549 xenografted mice compared to WT mice, whereas no significant expression was observed in TNFR2 KO mice xenografted with A549 lung cancer cells compared to TNFR2 KO mice." (PMID 38592583, 2024). "We found a statistical evidence of BDNF up-regulation in lung cancer, compared with their non-tumor counterparts." (PMID 26926340, 2016). "We also examined the expression of BDNF by western blot in HBE and other lung cancer cells." (PMID 26926340, 2016). "Immunohistochemical analysis revealed that the BDNF and TrkB reactive cell number between TNFR2 KO and TNFR2 KO mice xenografted with A549 lung cancer cells brains was not significant, whereas significant results were seen in WT and WT A549 lung cancer cells xenografted mouse brains." (PMID 38592583, 2024). "However, BDNF injection did not induce any change in SCZ-like behavior in WT mice xenografted with A549 lung cancer cells." (PMID 38592583, 2024). "To verify the roles of BDNF in mediating the effect of TNFR2 KO in lung tumor growth and SCZ, and expression of BDNF and TrkB, we injected BDNF (by intravenous injection, 160 μg/kg every 4 days for 28 days including the first day of xenograft) in our A549 lung cancer cells xenograft mice model." (PMID 38592583, 2024). "It was reported that BDNF binds to tyrosine kinase B (TrkB) receptor or P75 leads to the activation of PI3K/AKT, RAS/ERK, AMPK/ACC, PLC/PKC and JAK/STAT signalings, which resulting in tumorigenesis and progression of malignancies, including breast cancer, lung cancer and neuroblastoma cancer." (PMID 36417428, 2022). "Therefore, BDNF in culture supernatant was assessed in HBE and four lung cancer cell lines." (PMID 26926340, 2016). "Thus, BDNF-regulated STAT3 activation can further strengthen BDNF expression, which may be the reason for enhanced STAT3 and TrkB activation in lung cancer." (PMID 27456333, 2016). "Western blot analysis was used to detect BDNF expression in 10 SCC and 15 ADC cases of lung cancer and non-tumorous tissue distant from the primary tumor of the same case." (PMID 26926340, 2016). "However, it is not known whether STAT3 is also a mediator of BDNF/TrkB signaling in lung cancers." (PMID 27456333, 2016).
lung carcinoma (continued). "The expression of BDNF and TrkB by Western blotting was significantly increased in WT A549 lung cancer cells xenografted mice PFC compared to WT mice PFC, whereas the expression in TNFR2 KO mice xenografted with A549 lung cancer cells PFC was not significant compared to TNFR2 KO mice PFC." (PMID 38592583, 2024).
temporal lobe epilepsy (26 papers, 2011 to 2025). A localization-related (focal) form of epilepsy characterized by recurrent seizures that arise from foci within the temporal lobe, most commonly from its mesial aspect. "In a preclinical study, it was reported that the administration of perampanel, lacosamide, and their combination in experimental model of temporal lobe epilepsy in adult Wistar rats significantly elevated the hippocampal levels of BDNF." (PMID 40291844, 2025). "We cannot rule out the possibility that MEF2D is crucial to refine the proper levels of BDNF, as abnormally increased levels of BDNF have been observed in the hippocampus and cortex of patients with temporal lobe epilepsy." (PMID 38796067, 2024). "In the rat pilocarpine model of temporal lobe epilepsy, metformin attenuates epileptic seizure‐induced activation of BDNF/TrkB signalling." (PMID 37737447, 2023). "There are studies showing an increase in BDNF gene expression in the hippocampus and temporal cortex in patients with temporal lobe epilepsy." (PMID 36831706, 2023). "In another study, the glycolytic inhibitor, 2-deoxy-D-glucose, suppressed seizure activity in a model of temporal lobe epilepsy via an NRSF/CtBP-dependent repression of the brain-derived neurotrophic factor gene promoter." (PMID 37060501, 2023). "A high amount of BDNF exists in the brain tissue of patients with intractable temporal lobe epilepsy." (PMID 33262686, 2020). "In patients with temporal lobe epilepsy, an increase in both BDNF mRNA and protein levels was found in surgically resected hippocampus and temporal lobe tissues." (PMID 30524358, 2018). "As extensively reported, the dentate gyrus is an important structure implicated in seizures, and in vitro and in vivo studies have shown involvement of BDNF in the development of temporal lobe epilepsy." (PMID 23840662, 2013). "BDNF also plays a role in the pathogenesis of temporal lobe epilepsy (TLE) by enhancing neuronal outgrowth and mossy fiber sprouting." (PMID 24349101, 2013). "Brain-derived neurotrophic factor (BDNF)/tyrosine kinase B (TrkB) signaling, oxidative stress, and mitochondrial respiratory chain complex dysfunction contribute to temporal lobe epilepsy (TLE), but their regulatory links remain unclear." (PMID 41020886, 2025). "Furthermore, BDNF serum level is higher in epileptic patients and correlated with disease severity mainly in temporal lobe epilepsy." (PMID 37737447, 2023). "We have recently also shown that the synaptic concentrations of Arc (and BDNF) may change in chronic temporal lobe epilepsy, compared to normal controls." (PMID 38025262, 2023). "Second, in a rat kindling model of temporal lobe epilepsy, 2-DG reduced seizure progression by reducing the expression of brain-derived neurotrophic factor (BDNF) and its receptor, TrkB; this reduced expression is mediated by the decreasing of transcription factor NRSF caused by 2-DG administration." (PMID 33363507, 2020). "New evidence from human tissue resected from intractable epileptics shows that BDNF expression and action in human tissue are consistent with those in the rat, supporting the hypothesis that BDNF may play a role in human temporal lobe epilepsy." (PMID 22654603, 2012). "In addition, patients with temporal lobe epilepsy were found to have higher BDNF levels." (PMID 36831706, 2023). "Indeed, it is perhaps no coincidence that BDNF-immunoreactive fibers innervate the regions most vulnerable in temporal lobe epilepsy." (PMID 22654603, 2012). "The aim of this study was to evaluate the methylation profile of the BDNF and SLC6A4, two genes importantly involved in neuroplasticity, in patients with temporal lobe epilepsy (TLE) regarding the development or not of psychiatric comorbidities." (PMID 34912196, 2021).